FASTKD3 (FAST kinase domains 3)
Description:
Required for normal mitochondrial respiration. Increases steady-state levels and half-lives of a subset of mature mitochondrial mRNAs MT-ND2, MT-ND3, MT-CYTB, MT-CO2, and MT-ATP8/6. Promotes MT-CO1 mRNA translation and increases mitochondrial complex IV assembly and activity.
Synonyms: MGC5297; FLJ23274
Tractability: PROTAC: ubiquitination databases record sites on it; its protein half-life has been measured.
Gene: Protein-coding gene on chromosome 5 (7,859,159 to 7,869,055, reverse strand). Ensembl gene ENSG00000124279.
Subcellular location: Mitochondrion
Subcellular location (Human Protein Atlas): Mitochondria; Nucleoplasm
Gene Ontology:
Molecular function: protein binding; RNA binding
Biological process: mitochondrial respiratory chain complex IV assembly; positive regulation of mitochondrial translation; regulation of mitochondrial mRNA stability; mitochondrial RNA processing
Cellular component: mitochondrion; mitochondrial matrix; ribonucleoprotein granule
Genetic constraint (gnomAD): Loss-of-function variants: 37 observed, 42.74 expected, observed/expected ratio (o/e) 0.87, 90% interval 0.67 to 1.14. The upper end of that interval is the gene's LOEUF score, 1.14, which puts it in group 4 of 6, group 1 being the genes least tolerant of losing a copy. Missense variants: 663 observed, 720.47 expected, observed/expected ratio (o/e) 0.92, 90% interval 0.86 to 0.98. Synonymous variants: 256 observed, 275.33 expected, observed/expected ratio (o/e) 0.93, 90% interval 0.84 to 1.03.
Homologues: Orthologues: chimpanzee FASTKD3 (99% identical), macaque FASTKD3 (85% identical), pig FASTKD3 (76% identical), dog FASTKD3 (74% identical), guinea pig FASTKD3 (68% identical), rabbit FASTKD3 (68% identical), rat Fastkd3 (66% identical), mouse Fastkd3 (65% identical), tropical clawed frog fastkd3 (44% identical), zebrafish fastkd3 (39% identical). Paralogues in human: FASTKD1 (19% identical), TBRG4 (19% identical), FASTKD5 (18% identical), FASTK (16% identical), FASTKD2 (16% identical).
Diseases named in the same sentence as FASTKD3 in open-access papers:
FASTKD3 is named in the same sentence as 7 diseases in open-access papers, as found by Europe PMC text mining. Sharing a sentence is not in itself a finding about the gene and the disease. The quoted sentences say what the papers report.
lung carcinoma (3 papers, 2021 to 2023). "In particular, gene amplification was found for FASTK and FASTKD3 in ovarian and lung cancers, respectively, while increased mRNA levels of all FASTK members were found in esophageal, stomach, liver and lung cancers." (PMID 34888254, 2021). "FASTK and FASTKD3 alterations consisted mainly of amplifications that were seen in more than 8% of ovarian and lung cancers, respectively." (PMID 34768773, 2021). "While the associations of PTPRF and FASTKD3 with COPD are not as clear, links between these two genes and lung cancer prognosis suggest some degree of activity within the lung through their roles in apoptosis, cell growth and differentiation, and oncogenesis." (PMID 37143066, 2023).
cervical cancer (1 paper, 2009). A primary or metastatic malignant neoplasm involving the cervix. "Many of the genes, including BIRC2, BIRC3, ATF5, NUP62, FASTKD3, IDH3G, and POFUTI, have been found to be regulated by gains or losses in previous cervical cancer studies." (PMID 19911042, 2009).
Hypertension (1 paper, 2021). The presence of chronic increased pressure in the systemic arterial system. "The functions of HPS3, FASTKD3 and FIGNL1 have no direct or indirect association with the pathogenesis of hypertension, and the existing studies have not proved their association with hypertension." (PMID 34297769, 2021). "HPS3, FASTKD3 and FIGNL1 1 are not directly or indirectly associated with hypertension." (PMID 34297769, 2021).
cancer (3 papers, 2021 to 2022). A tumor composed of atypical neoplastic, often pleomorphic cells that invade other tissues. "FASTK genes were found upregulated in different types of cancer, and among the FASTK family, FASTKD3 mutations were found in 33 cancer types." (PMID 35682820, 2022). "In this study, our analysis of the TCGA sequencing data revealed that FASTK and especially FASTKD3 amplifications stand out as the most common genetic alterations of FASTK genes across 33 cancer types." (PMID 34768773, 2021). "As reviewed in the introduction, several studies have previously reported upregulation of FASTK, FASTKD1, FASTKD2 and FASTKD3 in certain types of cancer." (PMID 34768773, 2021). "Of note, FASTKD3 was found to be amplified in >8% of various types of cancer including LUSC, LUAD, ESCA and BLCA." (PMID 34768773, 2021). "FASTKD1, FASTKD3 and FASTKD5 were the FASTK genes most frequently mutated in cancers." (PMID 34768773, 2021). "In this regard, novel cancer-associated genes might remain to be identified in the amplified regions and, among these genes, FASTK and FASTKD3 could contribute to tumorigenesis in concert with oncogenes in the same amplicons." (PMID 34768773, 2021). "However, there are few reports on FASTKD3 and ZC3H12C involved in cancer." (PMID 36118863, 2022).
FASTKD3 also shares sentences with these, for which no sentence is quoted: Alzheimer disease (1 paper); emphysema (1); tumor (1).